PIP5K1B (phosphatidylinositol-4-phosphate 5-kinase type 1 beta)
Description:
Catalyzes the phosphorylation of phosphatidylinositol 4-phosphate (PtdIns(4)P/PI4P) to form phosphatidylinositol 4,5-bisphosphate (PtdIns(4,5)P2/PIP2), a lipid second messenger that regulates several cellular processes such as signal transduction, vesicle trafficking, actin cytoskeleton dynamics, cell adhesion, and cell motility (By similarity). PtdIns(4,5)P2 can directly act as a second messenger or can be utilized as a precursor to generate other second messengers: inositol 1,4,5-trisphosphate (IP3), diacylglycerol (DAG) or phosphatidylinositol-3,4,5-trisphosphate (PtdIns(3,4,5)P3/PIP3) (By similarity). Mediates RAC1-dependent reorganization of actin filaments. Contributes to the activation of phospholipase PLD2. Together with PIP5K1A, is required, after stimulation by G protein-coupled receptors, for the synthesis of IP3 that will induce stable platelet adhesion (By similarity).
Synonyms: STM7; MSS4
Tractability: Antibody: UniProt places it where antibodies can reach, with medium confidence; its Gene Ontology location is reachable by antibodies, with medium confidence. PROTAC: ubiquitination databases record sites on it; a small molecule that binds it is known.
Target class: Enzyme; Transferase
Gene: Protein-coding gene on chromosome 9 (68,705,190 to 69,009,191, forward strand). Ensembl gene ENSG00000107242.
Subcellular location: Cytoplasm, cytosol; Cell membrane; Endomembrane system
Subcellular location (Human Protein Atlas): Nucleoplasm; Vesicles
Pathways (Reactome):
Signal Transduction: PI5P, PP2A and IER3 Regulate PI3K/AKT Signaling; WNT mediated activation of DVL
Metabolism: Synthesis of PIPs at the plasma membrane
Gene Ontology:
Molecular function: protein binding; 1-phosphatidylinositol-3-phosphate 5-kinase activity; 1-phosphatidylinositol-4-phosphate 5-kinase activity; 1-phosphatidylinositol-5-kinase activity; phosphatidylinositol kinase activity
Biological process: phosphatidylinositol biosynthetic process; phosphatidylinositol phosphate biosynthetic process; regulation of phosphatidylinositol 3-kinase/protein kinase B signal transduction; phosphatidylinositol metabolic process
Cellular component: uropod; cytosol; plasma membrane; endomembrane system
Genetic constraint (gnomAD): Loss-of-function variants: 18 observed, 30.11 expected, observed/expected ratio (o/e) 0.6, 90% interval 0.41 to 0.89. The upper end of that interval is the gene's LOEUF score, 0.89, which puts it in group 3 of 6, group 1 being the genes least tolerant of losing a copy. Missense variants: 274 observed, 395.23 expected, observed/expected ratio (o/e) 0.69, 90% interval 0.63 to 0.77. Synonymous variants: 142 observed, 147.46 expected, observed/expected ratio (o/e) 0.96, 90% interval 0.84 to 1.11.
Homologues: Orthologues: chimpanzee PIP5K1B (99% identical), macaque PIP5K1B (99% identical), pig PIP5K1B (98% identical), rabbit PIP5K1B (97% identical), dog PIP5K1B (97% identical), mouse Pip5k1b (96% identical), rat Pip5k1b (96% identical), guinea pig PIP5K1B (87% identical), tropical clawed frog pip5k1b (81% identical), zebrafish pip5k1bb (72% identical), zebrafish pip5k1ba (65% identical). Paralogues in human: PIP5K1C (63% identical), PIP5K1A (58% identical), PIP4K2B (25% identical), PIP4K2C (23% identical), PIP4K2A (22% identical), PIP5KL1 (17% identical).
Diseases named in the same sentence as PIP5K1B in open-access papers:
PIP5K1B is named in the same sentence as 19 diseases in open-access papers, as found by Europe PMC text mining. Sharing a sentence is not in itself a finding about the gene and the disease. The quoted sentences say what the papers report.
adenoma (2 papers, 2022 to 2023). A neoplasm arising from the epithelium. "The gene encoding PIP5K1B, known to participate in the regulation of cell cycle, proliferation, migration and apoptosis was significantly overexpressed in POU1F1 adenomas." (PMID 35260162, 2022).
Breast Invasive Carcinoma (2 papers, 2018 to 2021). "Of importance, lower expression levels of the PDE9A, Iqca1, Sirpb1b, CD244, SP140, and PIP5k1b genes was found in the BC patients with unfavorable prognosis in terms of 5-year survival analysis (dataset of Breast Invasive Carcinoma [n = 1075] from TCGA)." (PMID 33426510, 2021).
colorectal cancer (2 papers, 2023 to 2026). A primary or metastatic malignant neoplasm that affects the colon or rectum. "In colorectal cancer, LRRC8A interacts with PIP5K1B to promote PIP2 (phosphatidylinositol-bisphosphate) production." (PMID 41439137, 2026). "For CT, the top gene was PIP5K1B which was related to PI3K/AKT signaling and seems to be involved in colorectal cancer development." (PMID 37956043, 2023).
asthma (1 paper, 2013). "Finally, we noted that, of the 12 vitamin D lung developmental genes transcriptomically related to asthma susceptibility, 4 – LAMP1, PIP5K1B, SCARB2, and TXNIP – were significantly differentially expressed upon administration of vitamin D to cells derived from asthmatic children." (PMID 24188128, 2013). "As mentioned, 4 of the developmental genes: LAMP1, PIP5K1B, SCARB2 and TXNIP, were differentially expressed in both asthma and upon stimulation of immortalized B-cells derived from asthmatics, suggesting a possible role of these genes in modulating the immune response in asthma." (PMID 24188128, 2013).
atherosclerosis (1 paper, 2017). A disease characterized by the build-up of fatty material and calcium deposition in the arterial wall resulting in partial or complete occlusion of the arterial lumen. "In a study that first reported on the kidney function of a general population, CX3CR1 rs3732379 SNP was associated with atherosclerosis of the coronary artery, SHROOM3 rs17319721 and PIP5K1B rs4744712 were associated with kidney disease." (PMID 29016630, 2017).
autism (1 paper, 2021). Persistent deficits in social interaction and communication and interaction as well as a markedly restricted repertoire of activity and interest as well as repetitive patterns of behavior. "A de novo splicing variant in PIP5K1B was also identified, which was reported to be associated with autism." (PMID 34630504, 2021).
dental caries (1 paper, 2020). The decay of a tooth, in which it becomes softened, discolored, and/or porous. "Interestingly, genetic variation within the human PIP5k1B gene has been identified as suggestively associated with pit-and-fissure dental caries in humans, a phenotype that has been shown to correlate with BMD." (PMID 30986855, 2020).
Friedreich ataxia (1 paper, 2013). An inherited condition that affects the nervous system and causes movement problems. "“Frataxin fracas” were the words used when referring to the frataxin-encoding gene (FXN) burst in as a motive to disqualify an alternative candidate gene, PIP5K1B, as an actor in Friedreich's ataxia (FRDA)." (PMID 24194977, 2013).
osteoporosis (1 paper, 2020). A condition of reduced bone mass, with decreased cortical thickness and a decrease in the number and size of the trabeculae of cancellous bone (but normal chemical composition), resulting in increased fracture incidence. "In present study, we discovered that PIP5k1β inhibited osteoclast formation and function while facilitating osteoblast differentiation, so that PIP5k1β−/− displayed an obvious osteoporosis phenotype." (PMID 30986855, 2020). "In the present work, we aimed to examine the function of PIP5k1β in osteoclastogenesis and osteogenesis to provide promising strategies for osteoporosis prevention and treatment." (PMID 30986855, 2020). "This suggests that PIP5k1β may serve a pivotal role in maintaining bone homeostasis and that investigation of the mechanisms behind its function may provide new strategies for the prevention and treatment of osteoporosis." (PMID 30986855, 2020).
ovarian carcinoma (1 paper, 2022). A malignant neoplasm originating from the surface ovarian epithelium. "It is well known that PIK3C2, PIP5K1B, AKT3 are either amplified or mutated in many cancers including ovarian cancer." (PMID 35205706, 2022). "We also observed that PIK3C2, PIP5K1B, and AKT3 are highly frequently amplified in the TCGA dataset of ovarian cancer." (PMID 35205706, 2022).
cancer (5 papers, 2016 to 2025). A tumor composed of atypical neoplastic, often pleomorphic cells that invade other tissues. "PIP5K1B may promote cell proliferation in certain cancer-related contexts, which appears to contrast with its potential protective role in PAS." (PMID 40419934, 2025).
bone disorder (1 paper, 2020). "Further investigation of the RANKL modulation of PIP5k1β expression is needed to increase our understanding of the biological role of PIP5k1β in maintaining bone homeostasis and to explore new targets for prevention and treatment of bone disorders." (PMID 30986855, 2020).
PIP5K1B also shares sentences with these, for which no sentence is quoted: breast carcinoma (2 papers); infection (1); Infertility (1); kidney disease (1); toxoplasmosis (1); tumor (1); Type 2 diabetes (1).